TLR2 (toll like receptor 2)
Diseases named in the same sentence as TLR2 in open-access papers (continued):
Sharing a sentence is not in itself a finding about the gene and the disease.
gastritis (12 papers, 2013 to 2023). Inflammation of the stomach. "Thus, global TLR2 deficiency would, on the one hand, decrease immune tolerance resulting in more severe gastritis and, on the other hand, decrease epithelial inflammatory responses resulting in less severe gastritis." (PMID 24058595, 2013). "For instance, H. pylori–induced gastritis patients showed higher expressions of TLR2, TLR4, and TNF–α in their gastric biopsies of while metaplasia and dysplasia patient samples exhibited higher TLR2 expression." (PMID 36317079, 2022). "In summary, our results demonstrate that TLR2/NF-κB-mediated PUMA induction contributes to the pathogenesis of H. pylori-induced gastritis by promoting GEC apoptosis." (PMID 32080167, 2020). "Helicobacter pylori is a bacterial pathogen that causes stomach inflammation and in gastric epithelial cells TRB3 enhances Toll-like receptor 2 (TLR2)-mediated NF-κB activation and chemokine induction in response to H. pylori LPS." (PMID 24490110, 2013). "Moreover, TLR2/NF-κB-mediated transcriptional regulation of PUMA contributes to the pathogenesis of H. pylori-infected gastritis." (PMID 32080167, 2020). "In addition, H&E/IF staining revealed that the TLR2-KO mice were highly resistant to H. pylori-induced gastritis due to blocked NF-κB activation and PUMA induction." (PMID 32080167, 2020). "We further investigated whether TLR2, which was previously implicated in the H. pylori-induced response, could mediate the activation of p-p65 and PUMA in H. pylori-induced gastritis." (PMID 32080167, 2020). "Furthermore, we used TLR2-KO mice to explore the role of TLR2 in H. pylori-induced gastritis." (PMID 32080167, 2020). "Thus, activation of TLR2, on the one hand, increases the immune tolerance favouring persistence of the bacterium in the stomach and, on the other hand, increases epithelial inflammatory responses resulting potentially in more severe gastritis." (PMID 25603825, 2015). "While TLR2, TLR4, TLR5, and TLR9 appear to be important for H. pylori recognition, their role in the evolution of gastritis to more advanced lesions remains unclear." (PMID 25101079, 2014). "Similar to the findings in TLR2 rs380499 gene polymorphism, we also noticed a significant association between CC variant genotype of NLRP3 rs10754558 gene polymorphism and an increased number of circulating neutrophils in children with H. pylori-negative gastritis." (PMID 35204842, 2022).
gram-positive bacterial infections (12 papers, 2011 to 2025). Infections caused by bacteria that retain the crystal violet stain (positive) when treated by the gram-staining method. "It has been demonstrated using TLR2-deficient mice that TLR2 contributes to the host defense against Gram-positive bacterial infection." (PMID 33763386, 2021). "Because a large proportion of preterm neonates are susceptible to Gram-positive bacterial infection during early life, we chose to characterize the development of systemic cytokine response in preterm pig blood challenged with TLR2 agonist." (PMID 27830761, 2016). "TLR2 knockout mice are hyper-susceptible to Gram positive bacterial infections, but resistant to Gram positive bacterial ligands, and humans with mutations in the TLR2 gene have altered Gram positive infection susceptibility." (PMID 23826682, 2013). "NOD2 is also involved in modulation of Toll-like receptor (TLR) signaling, and regarding this latter the recipient TLR2 R753Q variant has also been associated with presentation with septic shock and infection recurrence with gram-positive bacterial infections after OLT." (PMID 23977330, 2013). "Accordingly, it is possible that during Gram-positive bacterial infection, combined insults, including those driven via TLR2, may cause long-lasting functional or structural deficits." (PMID 21573120, 2011). "TLR2 is a sensor of cell wall products and generally considered to be a sensor for Gram-positive bacterial infections via its ability to detect lipoteichoic acid from bacterial cell walls." (PMID 29896111, 2018). "Interestingly, transcription of TLR2 and MyD88 are both coordinately up-regulated during human neonatal Gram-positive infection in vivo, highlighting how our murine model recapitulates the human neonatal response to Gram-positive bacterial infection." (PMID 22970147, 2012). "LPS (activator of TLR4) and LTA (activator of TLR2) were selected to mimic the Gram-negative and Gram-positive bacterial infections, respectively." (PMID 40226627, 2025). "On the one hand, considering that lungs have a high expression of TLR2 and that this signaling pathway is activated by Gram positive pathogens, a mixture of the MALP2 and Pam3CSK4 ligands was used to mimic the respiratory pro-inflammatory response induced Gram positive bacterial infections." (PMID 32414154, 2020).
Granuloma (12 papers, 2013 to 2025). A compact, organized collection of mature mononuclear phagocytes, which may be but is not necessarily accompanied by accessory features such as necrosis. "In animal models, TLR2 gene deletion was found to be an important factor in the development of granuloma formation." (PMID 32350353, 2020). "Manual counting of infected macrophage clusters showed a significantly lower number of granulomas in the tlr2 mutant." (PMID 31747871, 2019). "More importantly, the size of granuloma and the severity of the fibrosis in the livers of TLR2-/- mice were significantly reduced compared to that in WT mice." (PMID 30589840, 2018). "In the current investigation, however, we found a pro-mycobacterial role for TLR2, as a requirement to establish the FMs in granuloma." (PMID 27532872, 2016). "BCG-induced granulomas from wild-type mice displayed increased occurrence of FMs in the tissues when compared to that from tlr2-null mice." (PMID 27532872, 2016). "While 5–8 such granulomas were observed in the lungs of the WT mice, tlr2-KO mice were found to have 2–3 granulomas in their lungs." (PMID 27532872, 2016). "The TLR2-/-, TLR9-/- and TLR2/9-/- mice exposed to SR all demonstrated granuloma formation suggesting that additional PRRs must be involved in granuloma formation in HP." (PMID 24023674, 2013). "Importantly, the granuloma score was significantly reduced from 32.5 in the WT to 17.5 in the tlr2-KO mice, indicating the TLR2 dependency of mycobacteria-induced granulomas." (PMID 27532872, 2016). "Importantly, results from IHC and IF experiments suggested that while H37Rv- and BCG-induced granulomas from wild-type mice express elevated levels of JMJD3, ADRP and CD36, expression of these genes in granulomas from tlr2-null mice was significantly abrogated." (PMID 27532872, 2016). "IL-22 has been suggested to play a protective role in the disease by inhibiting CD4+ T cell migration and collagen deposition and the decrease in IL-22 in the TLR2/9-/- mice may explain the development of granulomas despite decreased T cell activation and TNFα production in these mice." (PMID 24023674, 2013). "To determine whether the decrease in neutrophils, IL-17 and activated CD4+ T cells in the lungs of TLR2/9-/- mice resulted in reduced development of granulomas, we examined H&E stained lung sections from WT and mutant mice that had been exposed to SR for 3 weeks." (PMID 24023674, 2013). "Non-vaccinated calves with focal lesions (33.3%) showed low levels of TLR2 immunolabeling at the intestine, along with a diffuse CD204 labeling of the granulomas, similar to those with progressive multifocal forms." (PMID 40646740, 2025). "IL-17A was the highest positively correlated gene to periapical granuloma, while TLR2, TLR4, VEGF, and MMP-9 were negatively correlated with the enriched pathways of granuloma." (PMID 34539639, 2021). "In this study, we conclusively demonstrate that Mtb infection in the absence of TLR2 results in poorly formed granulomas, progressive pulmonary pathology, and increased lung bacterial burden during chronic infection." (PMID 23785280, 2013). "Indeed, persistent TLR2-mediated activation of ATR has recently been found to promote polypoid macrophage differentiation, a feature of granulomas, indicating that this kinase cascade might play an important role in development of chronic infection." (PMID 31951200, 2020). "To determine whether TLRs 2 and 9 also control neutrophil recruitment throughout 3 weeks of repeated exposures (at which time granulomas develop) we exposed WT, TLR2-/-, TLR9-/-, and TLR2/9-/- mice to SR 3 times / week for 3 weeks and performed BAL one day after the last exposure." (PMID 24023674, 2013).
hyperlipidemia (12 papers, 2011 to 2025). "Considering that VLDLR is important in postprandial chylomicron and VLDL clearance, the upregulation of VLDLR is thought to lower serum lipids, which is opposite of the hyperlipidemia phenotype seen in both offspring-pLPS and TLR2-deficient offspring-pLPS." (PMID 31507457, 2019). "This suggests that, in the context of prenatal inflammatory stimulation, TLR4 is overactivated to compensate for the loss of TLR2, which likely contributes to the more severe hyperlipidemia phenotype in TLR2-deficient offspring-pLPS." (PMID 31507457, 2019). "However, unexpectedly, TLR2-deficient offspring-pLPS mice not only presented with an abnormal phenotype comparable to that of wild-type offspring-pLPS mice but also exhibited significantly more severe hyperlipidemia." (PMID 31507457, 2019). "Hyperlipidemia activates innate immunity by activating Toll-like receptor 2 (TLR-2) and TLR-4 pathways, leading to activation of inflammatory and pro-atherogenic genes in macrophages and endothelial cells." (PMID 31448091, 2019). "Periodontal tissues in ApoE−/− hyperlipidemia model rats are reported to exhibit more TRAP-positive multinuclear cells and increased TLR2 and TLR4 expression levels, suggesting that high oxLDL concentration effects osteoclastogenesis via the elevation of TLRs." (PMID 29859535, 2018). "In our study, macrophages from ApoE−/− mice showed inhibited transcription of TLR2, TREM-1, TREM-3, and CD14 in quiescent state, whereas only TREM-1 expression was influenced by hyperlipidemia in bacteria stimulated macrophages." (PMID 23977160, 2013). "Notably, hyperlipidemia stimulation significantly decreased the mRNA expression levels of TLR-4 and TLR-2 by 69.1% (P < 0.001) and 68.1% (P < 0.05), and 52.1% (P < 0.01) and 38.6% (P < 0.05), respectively, in PCSK9liver(−/−) and PCSK9liver(+/−) mice as compared to that of PCSK9liver(+/+) mice." (PMID 39963241, 2025). "Mechanistically, hyperlipidemia induced by HFD feeding acts as the first stimulation for TI via lysoPC stimulation, oxidized low-density lipoprotein (oxLDL) binding to CD36, TLR4 /TLR2 and nucleotide-binding domain, leucine-rich-containing family, pyrin domain-containing 3 (NLRP3) inflammasomes." (PMID 34859106, 2021). "Because such attenuation is not seen in wild-type mice, in which the expression of Tlr2 and Tlr4 was further elevated after long-term infection compared with short-term infection, the deletion of the ApoE gene and/or the resulting hyperlipidemia may have affected the endothelial response." (PMID 21625524, 2011).
non-alcoholic steatohepatitis (12 papers, 2010 to 2025). "Conversely, in mice fed with a diet deficient in methionine and choline (MCDD), TLR2 knockout exacerbates MCDD-induced nonalcoholic steatohepatitis." (PMID 31349604, 2019). "Akkermansia muciniphila protects against nonalcoholic steatohepatitis by modulating macrophage polarization and TLR2-activated γδT17 cells and improves cognitive function in aged mice." (PMID 39967592, 2025). "The activation of TLR signaling plays a key role in hepatic inflammation and fibrosis, with TLR4 and TLR2 having essential roles in the progression of non-alcoholic steatohepatitis." (PMID 39599705, 2024). "The activation of Toll-like receptor (TLR) signaling is key in the process of liver inflammation and fibrosis, with TLR4 and TLR2 serving crucial roles in the progression of non-alcoholic steatohepatitis." (PMID 39599705, 2024). "In non-alcoholic steatohepatitis, TLRs play important roles and it has been demonstrated that TLR2-enhanced expression of Nod-like receptor protein 3 via NF-kB, promotes NLRP3-inflammasome activation in concert with saturated fatty acid in Kupffer cells." (PMID 30057898, 2018). "A study in a mouse model of non-alcoholic steatohepatitis identified decreased miR-144 expression in Kupffer cells with consequent induction of TLR2." (PMID 30057898, 2018). "Mice lacking TLR2 gene exhibited notable reductions in inflammation, steatosis, and the development of non-alcoholic steatohepatitis." (PMID 38790653, 2024).
endophthalmitis (11 papers, 2011 to 2024). An infectious process affecting the internal structures of the eye. "We tested this hypothesis by comparing the pathogenesis of experimental B. cereus endophthalmitis in TLR2-deficient mice with that of infection in wild type mice." (PMID 22163046, 2011). "We have previously reported that during endophthalmitis progression, Bc stimulates activation of both TLR2 and TLR4 pathways, resulting in signal cascade initiation through both MyD88-dependent and MyD88-independent (TRIF-dependent) pathways, respectively." (PMID 38106476, 2023). "Together, these findings demonstrated that inhibition of the TLR2 and TLR4 pathways and infection with SlpA-deficient B. thuringiensis in experimental endophthalmitis had a similar outcome." (PMID 32117322, 2020). "We demonstrated that during B. cereus endophthalmitis, TLR2 and TLR4 each directly influenced the severity of intraocular inflammation." (PMID 32117322, 2020). "Our findings demonstrate for the first time that Bacillus SLP impacted endophthalmitis pathogenesis by activating both TLR2 and TLR4 pathways." (PMID 32117322, 2020). "Taken together, these results suggest a potential role for Bacillus SLP in host-bacterial interactions, as well as in endophthalmitis pathogenesis via TLR2- and TLR4-mediated pathways." (PMID 32117322, 2020). "Since TLR2 plays an important role in SA endophthalmitis, counter regulation analysis of TLR2 ligand pretreated retina or the use of retinas from TLR2 knockout mice showed the down-regulation of inflammatory regulatory genes." (PMID 26865111, 2016). "Downregulation of TLR2 in response to infection has been reported during experimental S. aureus endophthalmitis." (PMID 22163046, 2011). "TLR2 plays an important role in both B. cereus and S. aureus endophthalmitis." (PMID 29661181, 2018). "Moreover, we showed that TLR2-activation prior to SA infection attenuated the development of endophthalmitis in a mouse model." (PMID 26865111, 2016). "Because TLRs are integral to the initial recognition of organisms during infection, we hypothesized that the uniquely explosive immune response observed during B. cereus endophthalmitis is directly influenced by TLR2." (PMID 22163046, 2011). "To address this hypothesis, we compared the courses of experimental B. cereus endophthalmitis in wild type C57BL/6J mice to that of age-matched homozygous TLR2-/- mice." (PMID 22163046, 2011). "In addition to identifying SLP as an unexpected TLR4 agonist, we revealed for the first time that inhibiting SLP-mediated TLR2/4 activation in experimental endophthalmitis could reduce disease severity." (PMID 32117322, 2020). "TLR2 and TLR4 are key mediators of the innate immune response to bacterial pathogens during the early stages of endophthalmitis." (PMID 29661181, 2018). "This suggests that SLP is a potent stimulator of both TLR2 and TLR4 innate pathways, and may contribute to the production of inflammatory mediators during experimental endophthalmitis." (PMID 32117322, 2020). "During B. cereus endophthalmitis, the absence of TLR2 and TLR4 in mice resulted in less infiltration of PMNs and fibrin accumulation, and preserved retinal architecture." (PMID 32117322, 2020). "Here, we investigated whether inhibition of both TLR2 and TLR4 activation affected bacterial growth during experimental endophthalmitis." (PMID 32117322, 2020). "For experimental B. cereus endophthalmitis, the absence of TLR2 resulted in a diminished inflammatory environment when compared to controls, but there was still some degree of inflammation in B. cereus-infected TLR2−/− eyes." (PMID 24959742, 2014). "We hypothesized that Muller glia provides retinal innate defense in endophthalmitis via the action of TLR signaling and recently reported the expression of functional TLR2." (PMID 22253793, 2012). "The primary difference observed between endophthalmitis in wild type versus TLR2-/- mice was the lack of significant posterior segment inflammation." (PMID 22163046, 2011).
endophthalmitis (continued). "Although TLR2 appears to be essential for initial bacterial recognition and rapid inflammation during B. cereus endophthalmitis, upregulation of TLR2 may not be necessary once the organisms are recognized and the inflammatory cascade has begun." (PMID 22163046, 2011). "In the current study, PlyB did not activate TLR2 or TLR4, TLRs that impact B. cereus endophthalmitis pathogenesis." (PMID 37273201, 2023).
gastric tumor (11 papers, 2013 to 2024). "In murine and human gastric tumors, TLR2 appears upregulated and associates with a poorer overall survival in humans." (PMID 32424768, 2020). "Neutralisation of TLR2 is reported to be effective in suppressing TLR2-driven gastric responses and alleviating tumorigenesis in a murine gastric tumour model." (PMID 33922955, 2021). "STAT3 can directly up-regulate the epithelial expression of TLR2 in gastric tumors, which is related to the low survival rate of GC patients." (PMID 32831016, 2020). "Another recent study showed that STAT3-mediated upregulation of TLR2 expression on gastric epithelial cells promoted cell proliferation and survival, and inhibition of TLR2 suppressed gastric tumor formation." (PMID 27733853, 2016). "In addition, in mice, TLR2 was found to be the most significantly upregulated gene among the TLRs in gastric tumor samples, its expression being predominantly identified in tumor epithelial cells." (PMID 30863783, 2019). "In addition, TLR2 was found to be the most extensively expressed gene among all the TLRs in gastric tumors." (PMID 30863783, 2019). "We analyzed TLR2, TLR4 and RAGE gene expression in human gastric tumor cells using quantitative real-time PCR." (PMID 25652880, 2015).